DDX3X (DEAD-box helicase 3 X-linked)
Diseases named in the same sentence as DDX3X in open-access papers (continued):
Sharing a sentence is not in itself a finding about the gene and the disease.
medulloblastoma (continued). "Still, recurrent mutations of DDX3X have been reported in medulloblastoma (a common childhood hindbrain tumor), mainly in wingless-type MMTV integration site family (WNT)-activated medulloblastomas and sonic hedgehog (SHH)-activated medulloblastomas." (PMID 35874614, 2022). "DDX3X is involved in stress granule formation, and DDX3X mutants were shown to induce the hyper-assembly of stress granules in medulloblastoma." (PMID 35954483, 2022). "We thus conclude that these specific translation defects, rather than generalized effects on translation, are responsible for the observed cellular phenotypes and likely contribute to DDX3X-mutant medulloblastoma." (PMID 33460649, 2021). "It remains possible, however, that changes in SG dynamics play a role in DDX3X-mediated medulloblastoma." (PMID 33460649, 2021). "Specifically, in medulloblastomas and natural killer/T cell lymphoma (NKTCL), DDX3X represents one of the most frequently mutated genes." (PMID 34638314, 2021). "Half of WNT medulloblastoma patients from three cohorts harboured DDX3X variants (50%, 16/32), while the percentage of patients with SHH medulloblastoma was 11% (7/66)." (PMID 33627125, 2021). "This previous work has contributed greatly to our understanding of the role of DDX3X/Ded1 in medulloblastoma and cancer generally." (PMID 33460649, 2021). "In medulloblastoma, DDX3X also appears to augment cell mobility by increasing Rac1 mRNA translation and stabilizing the β-catenin protein, suggesting DDX3X has a role in Wnt signaling." (PMID 31906196, 2019). "DDX3X, which encodes a member of this family (DDX3), is especially intriguing given it is mutated recurrently in several cancers, most notably medulloblastoma (MB), a highly malignant cerebellar tumor." (PMID 27058758, 2016). "Especially, medulloblastoma, in which DDX3X has been shown to act as a driver gene, is similar in appearance and differentiation potential to neural stem and progenitor cells." (PMID 25343452, 2014). "Several studies have examined subsets of the medulloblastoma-associated DDX3X mutations in greater detail and documented various biochemical, molecular, and cellular defects associated with them (Comments column), suggesting that these phenotypes contribute to the role of DDX3X in medulloblastoma." (PMID 39062517, 2024). "Furthermore, PTCH1, DDX3X and SMO driver mutations characteristic to SHH medulloblastomas, and PRDM6 enhancer hijacking driver events found in Group 4-medulloblastomas associated with MuAt features (FDR<1%)." (PMID 37420249, 2023). "In addition, we analyzed the changes of proteins (APC, CTNNB1, DDX3X, PTEN, BCOR) associated with medulloblastomas in CB at the four developmental stages." (PMID 37400444, 2023). "Moreover, mutations in DDX3X are crucial for the proliferation and/or maintenance of the LRLP lineage, which is believed to be the cell-of-origin of WNT medulloblastoma." (PMID 33627125, 2021). "DDX3X has been shown to regulate this pathway through activation of casein kinase 1ε, although several DDX3X medulloblastoma-associated mutants did not have a major effect on Wnt transcriptional targets when tested previously." (PMID 33460649, 2021). "One of the most prominent findings from these studies was frequent mutations in the RNA helicase DDX3X, which had not previously been linked to medulloblastoma." (PMID 33460649, 2021). "From these analyses, we conclude that mutant DDX3X and loss of GSE1 act as drivers of SHH medulloblastoma tumorigenesis, while mutations in KDM3B may represent a passenger." (PMID 31204176, 2019). "The fact that CK1 activity is needed in Wnt/β-catenin and SHH signaling suggested that mutations in DDX3X might affect CK1 activity and that this could be the reason why they cluster in the Wnt and SHH medulloblastoma tumor groups." (PMID 29222110, 2018).
medulloblastoma (continued). "Indeed, genome sequencing studies by our group and others have identified DDX3X mutations in over 50% of Wingless (WNT) subgroup medulloblastomas in children and upwards of 60% of Sonic hedgehog (SHH) subgroup medulloblastomas in adults." (PMID 27058758, 2016). "It is also possible that another function of DDX3X, such as its role in innate immunity, may be affected by the medulloblastoma mutations, but such phenotypes have not been reported either." (PMID 39062517, 2024). "As a cautionary note, however, these experiments were performed with Ddx3x knockouts rather than any of the identified mutations, so these observed effects may be different in actual medulloblastoma patients." (PMID 39062517, 2024). "Interestingly, a mutation in the Walker A motif (K230A, not found in medulloblastoma) that rendered DDX3X completely ATPase-defective had a dominant growth defect, suggesting that none of the medulloblastoma-associated mutations are as severe." (PMID 39062517, 2024). "In 2016, Oh and colleagues analyzed mRNA levels in SHH-subtype medulloblastoma patients, and via gene set enrichment analyses, they showed that the mRNAs of genes correlated with translation initiation had elevated levels in tumors with wild-type DDX3X compared with those of DDX3X-mutant tumors." (PMID 39062517, 2024). "Although no gene amplifications or deletions of DDX3X have been reported in medulloblastoma, it remains possible that the identified mutations may affect protein stability." (PMID 33460649, 2021). "The medulloblastoma-associated mutations in DDX3X are not found in these regions, however." (PMID 33460649, 2021). "Thus, we speculate that similar mechanisms may regulate DDX3X translation targets in medulloblastoma." (PMID 33460649, 2021). "The finding that mutations in DDX3X cause the activation of other CK1 isoforms besides CK1ε in living cells is striking and might contribute to the pathological effects of DDX3X mutations found in medulloblastoma." (PMID 29222110, 2018). "On a tissue level, DDX3X may play a role in maintaining the lineage of rhombic lip progenitor cells (LRLPs), the primary source of WNT-subgroup medulloblastomas." (PMID 39062517, 2024). "Efforts to identify the critical target mRNAs of DDX3X in medulloblastoma have not yet conclusively defined such a subset." (PMID 39062517, 2024). "However, there is increasing evidence that DDX3X is specifically involved in non-canonical translation initiation during cellular stress, which likely contributes to the altered translational responses to stress observed with medulloblastoma-associated DDX3X mutants." (PMID 36393867, 2022). "Interestingly, studies of DDX3X mutations identified in natural killer/T-cell lymphoma and intellectual disability syndromes have suggested that the mutations in these diseases are quite severe and include frameshifts and nonsense mutations that are not present in medulloblastoma." (PMID 33460649, 2021). "While previous studies have identified defects in a select few mutants, it is unclear whether they are generally common to the spectrum of DDX3X/DED1 mutations, and thus the identified phenotypes may not be key contributors to medulloblastoma pathology." (PMID 33460649, 2021).
colorectal cancer (38 papers, 2015 to 2025). A primary or metastatic malignant neoplasm that affects the colon or rectum. "Nuclear localization of DDX3X has been detected in breast and colorectal cancer tissues and is correlated with other factors associated with poor prognosis." (PMID 33627125, 2021). "In colorectal cancer, DDX3X expression has been detected, and positive associations between DDX3 and KRAS, YAP1, and SIX2 have been observed in KRAS wild-type patients." (PMID 31906196, 2019). "Both KRAS wild-type and mutant cohorts of colorectal cancer patients were shown to exhibit high DDX3X expression associated with poor overall survival and relapse-free survival." (PMID 31906196, 2019). "Some unique interactors of DDX3X are associated with colorectal cancer." (PMID 35954483, 2022). "The similarity of the high DDX3X gene signature to those related to the activation of colorectal cancer metastasis and planar cell polarity (PCP) signaling was identified." (PMID 37371098, 2023). "DDX3X expression predicted better survival rate in colorectal cancer, urothelial cancer, lung cancer and gastric cancer." (PMID 37371098, 2023). "Although nuclear DDX3X has been found to predict poor outcomes in breast and colorectal cancer, the pathological functions of DDX3X in cancer are controversial." (PMID 37988165, 2023). "DDX3X has already been described as an activator of AKT in colorectal cancer, promoting metastasis via the β-catenin/ZEB1 axis." (PMID 35954483, 2022). "This suggested that modulation of the Snail/E-cadherin pathway by DDX3X suppresses colorectal cancer cell metastasis." (PMID 35954483, 2022). "In colorectal cancer and osteosarcoma, DDX3X prevents multipolar mitosis through inactivation and coalescence of excess centrosomes." (PMID 33627125, 2021). "AVNs targeting DDX3X lead to mitochondrial swelling and increase ROS production, eventually leading to cell death in colorectal cancer." (PMID 33627125, 2021). "The YAP1/SIX2 axis is responsible for DDX3X-induced cell invasiveness in colorectal cancer harbouring wild-type KRAS." (PMID 33627125, 2021). "In a colorectal cancer, knocking down DDX3X expression promoted cancer cell migration and invasion, and increased tumor metastasis in an animal model via the regulation of the Snail/E-cadherin pathway." (PMID 31906196, 2019). "In colorectal cancer, high DDX3X protein levels were shown to predict good overall survival and recurrence-free survival in a 221-case cohort, and the RNA expression of DDX3X had significant prognostic value when evaluated by RNA-Seq and microarray platforms." (PMID 31906196, 2019). "DDX3X enhances tumor invasion or cell growth in colorectal cancer." (PMID 40885716, 2025). "Given that TALIN-1, MRE11, and CCT8 interact with E-cadherin, that FASN, FLNA, and DDX3X are implicated in EMT, and that FKBP4 expression is upregulated in colon cancers, we examined E-cadherin expression in human colorectal carcinoma HCT116 cells under the FKBP4 knockdown." (PMID 41203126, 2025). "Other studies have reported an oncogenic role for DDX3X in colorectal cancer." (PMID 35626643, 2022). "Low levels of DDX3X expression have been associated with poor prognosis in patients with colorectal cancer and in patients who are non-smokers with oral cancer, while a high expression of DDX3X is associated with poor prognosis in gliomas." (PMID 35626643, 2022). "However, a different study reported that in colorectal cancer DDX3X is also a tumor suppressor factor." (PMID 35954483, 2022). "Furthermore, knocking down Snail significantly reduced the migration and invasion capacities of cells with DDX3X knockdown, indicating that DDX3X represses colorectal cancer cell metastasis by mediating the Snail/E-cadherin pathway." (PMID 33627125, 2021). "However, the specific molecular mechanisms by which DDX3X promotes metastasis are different in colorectal cancers harbouring wild-type or mutant KRAS." (PMID 33627125, 2021).
colorectal cancer (continued). "Furthermore, the prognostic power of DDX3X has been specifically correlated with the nuclear DDX3X expression level in both breast and colorectal cancers." (PMID 31906196, 2019). "Furthermore, the β-catenin/ZEB1 axis is activated by DDX3X-dependent KRAS transcription to promote colorectal cancer invasion." (PMID 31906196, 2019). "Moreover, DDX3X silencing by siRNA causes reductions in both TCF-4 reporter activity and TCF-4-mediated modulation of downstream target genes in colorectal cancer, which leads to reduced proliferation and G1 arrest." (PMID 31906196, 2019). "The gene designated DEAD-box RNA helicase 3X (DDX3X) encodes an RNA helicase protein that assumes a central role in the development of several carcinomas, such as renal cell carcinoma, hepatocellular carcinoma (HCC), prostate cancer, lung cancer, and colorectal cancer." (PMID 38316768, 2024). "However, it cannot be excluded that the dual role of DDX3X observed in colorectal cancer could possibly be due to the use of different cell lines." (PMID 35954483, 2022). "However, the actual role of DDX3X in colorectal cancer needs to be verified." (PMID 33627125, 2021). "We depleted endogenous DDX3X using an inducible degron system, employing a male-derived colorectal cancer HCT 116 cell line with stably integrated auxin-activated OSTIR1 machinery, where the endogenous DDX3X gene was tagged with a degradation tag." (PMID 38697667, 2024). "By stabilising DDX3X, USP7 increases Wnt/beta‐catenin signalling, which has previously been demonstrated to be strongly correlated with colorectal cancer cell invasiveness." (PMID 38279869, 2024). "We depleted endogenous DDX3X using an inducible degron system, employing a male-derived colorectal cancer HCT 116 cell line with stably integrated auxin-activated OSTIR1 machinery, where the endogenous DDX3X gene was tagged with a degradation tag19,24." (PMID 37745530, 2023). "In addition to promoting metastasis, the DDX3X-induced YAP1/SIX2 axis might be responsible for resistance to treatment with the anti-EGFR antibody cetuximab (CTX) in colorectal cancer harbouring wild-type KRAS via enhanced autophagy and anti-apoptotic mechanisms." (PMID 33627125, 2021). "In addition, the CK1ε/Dvl2/β-catenin axis was shown to be activated upon DDX3X overexpression to increase colorectal cancer invasion and metastasis in an animal model, whereas these effects could be blocked by inhibitors of CK1ε (PF4800567) and β-catenin/TCF signaling (XAV939)." (PMID 31906196, 2019). "In order to dissect the similarities and differences between the functions of DDX3X and DDX3Y, we used a cell line we generated to rapidly and efficiently degrade endogenous DDX3 protein X in human male-derived colorectal cancer HCT 116 cells, which show a stable diploid karyotype." (PMID 34535544, 2021). "In addition, DDX3X-dependent aggressiveness and drug resistance to cetuximab treatment have been revealed to be modulated by the YAP1-SIX2 signaling axis in KRAS wild-type colorectal cancer in both cell and animal models." (PMID 31906196, 2019).
lung carcinoma (36 papers, 2014 to 2025). "Given the downregulation of CBS, GCLC, and GCLM in DDX3X-deficient lung cancer cells, we then questioned which enzyme primarily mediates the effects of DDX3X inhibition." (PMID 40885716, 2025). "In this study, we present evidence that the loss of DDX3X significantly delays tumor progression in various KRAS-driven lung cancer models." (PMID 40885716, 2025). "On the contrary, oral and lung cancer patients harboring a low DDX3X expression level were reported to associate poor prognosis." (PMID 32326089, 2020). "Loss of DDX3X function induced by shRNA or RK-33 addition elicits G1 cell cycle arrest and apoptosis in lung cancer that impairs Wnt signaling." (PMID 31906196, 2019). "In lung cancer, high expression of DDX3X has been associated with more aggressive tumor behavior." (PMID 40885716, 2025). "Our data suggested that DDX3X may represent a novel therapeutic target for overcoming intratumor heterogeneity in lung cancer patients harboring EGFR-activating mutations." (PMID 25343452, 2014). "Similarly, in lung cancer patient-derived organoids (PDOs), which faithfully reproduce the morphological and genomic features of human lung tumors, we observed that both the size and viability were markedly decreased in DDX3X deficient lung tumor organoids." (PMID 40885716, 2025). "Inhibition of DDX3X disrupts cysteine and glutathione metabolism, thereby inducing ferroptosis in lung cancer cells." (PMID 40885716, 2025). "In our study, by utilizing a spontaneous KRAS-driven lung cancer model, human lung cancer organoids, and cell lines, we have unveiled a pivotal role of DDX3X in lung cancer progression." (PMID 40885716, 2025). "To investigate the correlation between DDX3X expression and lung cancer patient prognosis, we conducted a comprehensive analysis of survival data from lung cancer cases profiled by TCGA." (PMID 40885716, 2025). "While previous studies have highlighted DDX3X multifaceted roles in lung cancer progression and its potential as a therapeutic target, a comprehensive understanding of its involvement in lung cancer necessitates further in-depth investigations." (PMID 40885716, 2025). "Lastly, we uncovered that DDX3X controls METTL16 transcription through a direct interaction with JUND transcripts, thus delineating an intact pathway elucidating how DDX3X regulates lung cancer progression." (PMID 40885716, 2025). "To explore the role of DDX3X in lung cancer, we initially bred Ddx3xfl/ fl mice to lox-stop-lox-KrasG12D mice to generate KrasG12D;Ddx3xfl/fl and KrasG12D;Ddx3xfl/y offspring." (PMID 40885716, 2025). "Specifically, inhibiting DDX3X disrupts cysteine and glutathione anabolism, consequently inducing ferroptosis in lung cancer cells." (PMID 40885716, 2025). "Our findings reveal that DDX3X serves as a key regulator of cysteine and glutathione metabolism, thereby controlling ferroptosis in lung cancer cells." (PMID 40885716, 2025). "To ensure these effects were not cell-line specific, we investigated the impact of J8 and J10 in two other lung cancer cell lines with elevated DDX3X expression, NCI-H460 and NCI-H1975, obtaining similar results." (PMID 40885716, 2025). "To study the role of DDX3X in lung cancer progression, we undertook a label-free proteomic analysis using DDX3X knockdown (shDDX3X) A549 cells." (PMID 40885716, 2025).